TG (thyroglobulin)
Diseases named in the same sentence as TG in open-access papers (continued):
Sharing a sentence is not in itself a finding about the gene and the disease.
thyroid cancer (continued). "Thyroglobulin is an antibody specially expressed in normal thyroid and thyroid carcinoma, which we can use in the differential diagnosis of lung carcinoma and thyroid carcinoma." (PMID 23414265, 2013). "Screening ultrasound of the neck and tumor marker (thyroglobulin) should be performed on all patients with differentiated thyroid cancer,per accepted guidelines." (PMID 22530159, 2012). "Differentiated thyroid carcinomas have the ability to capture and organify iodine and also synthesize and release thyroglobulin." (PMID 23486990, 2011). "Two of the earliest biomarkers discovered in thyroid cancer stemmed from the seminal work that established serum assays for measuring serum thyroglobulin and calcitonin levels." (PMID 24281099, 2010). "The serum-based biomarkers, calcitonin and thyroglobulin, provided the impetus for future research in the discovery of biomarkers in thyroid cancer." (PMID 24281099, 2010). "Measurement of thyroglobulin (TG) in the FNAB needle rinse from the cervical lymph nodes has been employed for detecting recurrent thyroid cancer in patients who have undergone total thyroidectomy and 131I therapy for differentiated thyroid cancer." (PMID 18237420, 2008). "These thyroid cancers also producethyroglobulin, and elevated thyroglobulin levels following definitive therapycan signify recurrent disease." (PMID 19125177, 2008). "Treatment of human thyroid cancer cells lineswith thiazolidinediones inhibits cell proliferation and induces increasedexpression of markers of thyroid cell differentiation such as thyroglobulin,sodium-iodine symporter, thyroperoxidase, and TSH receptor." (PMID 19125177, 2008). "It has been suggested that thyroglobulin measurements can be performed from the aspirate of the cystic lesion and if this is measurable, then a metastasis from a thyroid carcinoma is very likely." (PMID 19061516, 2008). "Thyroglobulin (Tg) is a cost-effective and essential biomarker for monitoring differentiated thyroid cancer (DTC) follow-up, especially for low- and intermediate-risk patients with excellent treatment response, as per thyroid cancer guidelines." (PMID 39298113, 2025). "The rise in thyroglobulin concentration could be indicative of a recurrence of thyroid cancer, requiring further workup." (PMID 39974195, 2025). "Thyroglobulin has been identified as a marker for thyroid cancer monitoring." (PMID 40969723, 2025). "Combined FISH and IHC identified microchimeric cells that expressed thyroglobulin—a protein exclusively synthesized by thyroid cells, often used as a marker for thyroid cancer detection and monitoring due to its role in the production of thyroid hormones, in both tumor and normal tissues." (PMID 39945850, 2025). "Thyroglobulin and thyroglobulin antibodies were introduced between the second and third editions of both organizations; these blood tests continue to play a vital role today in the follow-up of patients with thyroid cancer." (PMID 40352024, 2025). "Thyroglobulin values are a marker of residual or recurrent thyroid carcinoma." (PMID 39963649, 2025). "Additionally, thyroglobulin is a precursor to thyroid hormones and a crucial tumor marker for differentiated thyroid carcinoma." (PMID 39974195, 2025). "Monitoring for recurrence of thyroid cancer post-total thyroidectomy is carried out by serial measurements of serum thyroglobulin levels, but this is limited by variations in results of different assays and the interference of serum thyroglobulin antibodies." (PMID 39335101, 2024). "Stimulation of TSHR by TSH secreted in the pituitary gland increases the synthesis of H2O2, which is the substrate of thyroperoxidase in thyroglobulin iodination and thyroid hormone synthesis, contributing to the high level of oxidative stress in thyroid cancer patients." (PMID 39180118, 2024).
thyroid cancer (continued). "Furthermore, the expression level of thyroglobulin, which is a differentiation marker of thyroid cancer, was lower in the solid component of the tumor than in the well-differentiated areas." (PMID 38598167, 2024). "For thyroid cancer, mAbs may be designed to target thyroid cancer cell‐specific markers, such as thyroglobulin and the thyroid‐stimulating hormone receptor." (PMID 38874523, 2024). "Similar patterns are observed in patients without the BRAF mutation, highlighting the value of thyroglobulin and calcitonin as prognostic markers for thyroid cancer patients." (PMID 39767732, 2024). "Moreover, serum thyroglobulin (Tg) is a vital tool in identifying thyroid cancer recurrence after total thyroidectomy." (PMID 37762070, 2023). "Therefore, it is important to evaluate serum thyroglobulin in a long-term follow-up in cases of thyroid cancer." (PMID 36176008, 2022). "Thyroglobulin, a large glycoprotein secreted both by normal thyroid tissue and by thyroid cancer cells is believed to be a useful predictor of persistent or recurrent disease as well as successful ablation of the thyroid remnant and universally recommended in the follow-up of all patients with DTC." (PMID 35860552, 2022). "However, Serum circulating antibodies, i.e., anti-thyroglobulin antibodies, anti-thyroid peroxidase and thyroid hormones in euthyroid thyroid cancer patients and healthy volunteers, are shown in." (PMID 35399732, 2022). "Only 20% to 30% of anaplastic follicular cell-derived thyroid carcinomas stain for thyroglobulin." (PMID 35328664, 2022). "In current practice, surveillance for thyroid cancer recurrence currently relies on serum biomarkers (including thyroglobulin in differentiated thyroid cancer (DTC) and calcitonin in medullary thyroid cancer (MTC)), radiological screening and invasive biopsies." (PMID 34298656, 2021). "However, 23–29% of patients with well-differentiated thyroid cancers express thyroglobulin antibodies thus making surveillance of thyroid cancer recurrence difficult." (PMID 34475951, 2021). "Serum thyroglobulin (TG), tumour marker for thyroid cancer, takes 4 weeks for complete clearance due to its long half-life, and might be undetectable in 12% of structural disease patients." (PMID 34512731, 2021). "For thyroid gland cancer prediction, thyroglobulin antibody in serum or plasma by immunoassay (2.69%), thyroglobulin in serum or plasma (0.58%), T4 (thyroxine) (0.62%), and gene telomerase reverse transcriptase (TERT) (SHAP value 0.59%) were found to be the major contributors." (PMID 34032581, 2021). "The cut-off was much lower than reported for differentiated thyroid cancers and wash-out levels for thyroglobulin, but this was explained due to differences in the respective amounts of Tg and Ct within the metastatic cells or released into the interstitial fluid during needle aspiration." (PMID 34519193, 2021). "Serum Cyfra 21.1 level in thyroid cancer patients might be used as an alternative biomarker to predict tumor progression, especially in cases with undetectable or unmonitored thyroglobulin because of thyroglobulin antibody." (PMID 33671989, 2021). "Dedifferentiated thyroid cancers are commonly defined as differentiated or poorly differentiated thyroid cancers, which, during tumor progression, lose their ability to uptake and concentrate radioiodine and produce thyroglobulin in some cases." (PMID 34748583, 2021). "In addition, cfRNA will address the issue of anti-thyroglobulin antibodies (present in 25% of thyroid cancer patients), that affects the reliability of thyroglobulin immunoassay." (PMID 34512731, 2021). "In addition, the presence of anti-thyroglobulin antibody in 25% of thyroid cancer patients affects the reliability of Tg assay." (PMID 33158279, 2020). "In these cases, the use of RAI could facilitate the use of serum thyroglobulin measurements in the thyroid cancer follow-up." (PMID 30462807, 2018).
thyroid cancer (continued). "Thyroglobulin (Tg) measurements assess recurrence in post-thyroidectomy thyroid cancer patients." (PMID 29221487, 2017). "In thyroid cancer, the importance of TGAb measurement was stressed because it could interfere with the measurement of thyroglobulin levels." (PMID 28678169, 2017). "Therefore, radioiodine uptake and thyroglobulin production by thyroid cancers are increased by RA treatment." (PMID 29085335, 2017). "Previous studies have indicated that preoperative serum thyroglobulin levels could be a predictor of differentiated thyroid cancer." (PMID 27446209, 2016). "131I scan and serum thyroglobulin are widely employed during the follow up of thyroid cancer and in the assessment of the best therapy to use after surgery, while immunohistochemical stain for thyroglobulin and TTF-1 is often essential in pathologic diagnosis as it has been in our experience." (PMID 25358556, 2014). "TTF-1 has been shown to be positive in primary lung adenocarcinoma and in the majority of primary thyroid cancers; therefore, clinical presentation and the use of thyroglobulin staining may be important for the final diagnosis." (PMID 24455357, 2013). "Papillary thyroid carcinomas (PTCs) are the most frequent cancers of the thyroid gland, and they are usually well differentiated given their ability to i) take up iodine, ii) secrete thyroglobulin (TG), and iii) be responsive to thyroid-stimulating hormone (TSH; Nikiforov & Nikiforova 2011)." (PMID 24014739, 2013). "In a previous pilot study we demonstrated that six recently identified marker genes (ADM3/HGD1/LGALS3/PLAB/TFF3/TG) can be successfully applied for a molecular discrimination of benign and malignant thyroid tumours including follicular thyroid neoplasia using surgically removed tissue samples." (PMID 22223087, 2012). "Thyroglobulin promoter was reported to target thyroid cancer." (PMID 22220168, 2011). "For treatment purposes, no studies to date have conclusively shown that adjuvant radioactive iodine therapy can improve this already excellent recurrence risk and ablative doses of this nuclear isotope may be used to facilitate follow-up of thyroglobulin levels as a thyroid cancer marker." (PMID 39272954, 2024). "Our previous study showed that expression of urinary exosomal (UEx) thyroglobulin protein was significantly higher in patients with T3 stage or lymph node metastasis than those with T1–2 stage, suggesting UEx thyroglobulin expression correlated with the severity of thyroid cancer progression." (PMID 36672532, 2022). "Except for BRAF, HRAS, NRAS and TG, whose involvement in PTC is deeply revealed, for the other commonly mutated genes in all tumor stages, we further assayed the relationship between TCGA data, the RNA expression level of thyroid cancer-derived cell lines and their mutational status." (PMID 35996174, 2022). "The absence of thyroglobulin staining may comply with poorly differentiated thyroid cancer (PDTC) or with loss of thyroglobulin expression in cell culture in absence of TSH." (PMID 33878728, 2021). "Since the measurement of thyroglobulin (TG) in FNA washout was first proposed as a supplementary method to FNAC for the detection of cervical lymph nodes metastases in 1992, growing numbers of studies have focused on the diagnostic performance of markers in FNA washout in thyroid cancer." (PMID 34689799, 2021). "In addition, detection of expression of tumour‐ or tissue‐specific markers was included: for hepatocellular carcinoma, alpha‐faetoprotein; for thyroid carcinoma, thyroglobulin and sodium:iodide symporter (NIS) and for ovarian cancer, cancer antigen 125 (CA‐125)." (PMID 26178530, 2016). "The RRA may also be avoided in low risk well-differentiated thyroid cancer with postsurgical stimulated thyroglobulin (sTg) < 1 ng/mL, an approach not yet approved by American Thyroid Association (ATA)." (PMID 24987542, 2014).
thyroid cancer (continued). "Measurement of thyroglobulin (Tg) protein in the washout of the needle used for fine needle aspiration biopsy cytology (FNAB-C) has been shown to increase the sensitivity of FNAB-C in identifying cervical lymph node (CLN) metastasis from well-differentiated thyroid cancer (TC)." (PMID 23421519, 2013). "With RF ablation of recurrent thyroid cancers, the mean volume reduction has been reported to be 56–93%, and with 42–58% of the nodules disappearing completely, 64% of the patients experiencing symptom improvement, and with the serum thyroglobulin concentration decreasing." (PMID 23133449, 2012). "However, in the presence of thyroid cancer, thyroglobulin levels may increase." (PMID 39744583, 2025). "This study highlights the correlation between thyroglobulin and calcitonin levels, the presence of the BRAF gene, and the disease stage, especially regarding thyroid cancer diagnosis and prognosis." (PMID 39767732, 2024). "An in vivo study found that knockdown of SBP1 promoted the expression of thyroid stimulating hormone receptors, thyroglobulin and NIS, as well as inhibited the growth and progression of thyroid cancer tumors." (PMID 37684566, 2023). "Our study reported that the SLC5A8 methylation positivity rate was associated with high thyroglobulin and cholesterol levels, which may suggest that dysregulation of the SLC5A8 gene is involved in widespread metabolic disturbances in patients with thyroid adenoma and thyroid cancer." (PMID 38007446, 2023). "Thyroid specific proteins, such as thyroperoxidase (TPO), thyroglobulin (TG), and sodium/iodide symporter (NIS), have been shown to be downregulated in thyroid cancer." (PMID 36497320, 2022). "Unfortunately, her thyroglobulin continued to increase post-radioactive iodine (RAI) treatment, indicating persistent and/or recurrent thyroid cancer." (PMID 34595070, 2021). "Effective radioiodide therapy of metastatic thyroid cancers requires uptake of radioiodide via the sodium/iodide symporter (NIS), and optimally, its incorporation into tyrosine residues of thyroglobulin to increase the residence time of the isotope." (PMID 30038597, 2018). "The expression of TG, NIS, PDS, and TPO was significantly lower in pediatric thyroid carcinomas compared to the normal thyroid tissue (P < 0.05)." (PMID 27022395, 2016). "Differentiated thyroid carcinomas can concentrate iodine, express thyroid stimulating hormone (TSH) receptor, and produce thyroglobulin (Tg), whereas poorly differentiated or undifferentiated carcinomas typically do not." (PMID 23193402, 2012). "Some proteins' alteration was found in thyroid cancer, such as CK19, TG, Ki67, Calcitonin, TTF-1, BRAF, RET, HBME-1, SERPINA1, TfR1/CD71, FHL1 and galectin-3." (PMID 22188859, 2011). "Retinoids have been reported to induce the expression of TPO, TG, and NIS mRNAs in thyroid carcinoma cell lines." (PMID 18682709, 2008). "In follicular and aplastic thyroid cancer cell lines, a low concentration of FR901228 (1 ng ml−1) increased both thyroglobulin, the transporter for iodine and radioiodine accumulation." (PMID 14520435, 2003). "This is because ATC is a poorly differentiated form of thyroid cancer that usually does not produce significant amounts of thyroglobulin." (PMID 39744583, 2025). "FOXE1 regulates the transcription of thyroglobulin (TG), thyroperoxidase (TPO), NKX2.1, PAX8, Sodium/Iodine Symporter (NIS), and DUOX2, genes required for hormone synthesis, and also regulates PDGFA and ZEB1 in thyroid cancer." (PMID 39588344, 2024). "The serum thyroglobulin level test is not typically performed during patient evaluations for TNs due to its lack of specificity and sensitivity in ruling out thyroid cancer." (PMID 38352091, 2024). "The detection of thyroid-specific proteins, such as thyroglobulin (Tg), thyroid peroxidase (TPO) and thyroid stimulating hormone receptor (TSHR), may reflect the differentiation ability of thyroid cancer cells." (PMID 39349421, 2024).
thyroid cancer (continued). "Furthermore, overexpression of SBP1 inhibited cellular differentiation of differentiated thyroid cancer cell line FTC-133, as indicated by decreased expression of thyroid stimulating hormone receptors, thyroglobulin and NIS." (PMID 37684566, 2023). "Next, we evaluated the expressions of thyroid transcription factor (TTF)-1 and − 2 as well as the expression of differentiation related genes, such as thyroid stimulating hormone receptor (TSH-R), thyroglobulin (TG) and sodium/iodide symporter (NIS) in thyroid cancer cell lines." (PMID 37684566, 2023). "Immunohistochemically, all tumor parts were negative for thyroglobulin, providing further evidence that this entity does not belong to the follicular epithelial cell-derived thyroid carcinoma group." (PMID 37249797, 2023). "We obtained our sporadic thyroid cancer mouse model TgCreERT2;BrafCA/+ by crossing the established BrafCA and TgCreERT2 mouse lines to conditionally express BRAFV600E in the thyroid under control of the thyroglobulin (Tg) promoter, as previously reported." (PMID 34379110, 2022). "Utility of thyroid-specific mRNA transcripts such as thyroid peroxidase (TPO), sodium-iodide symporter (NIS), thyroglobulin (TG), and thyroid stimulating hormone receptor (TSHR) in predicting thyroid cancer recurrences and metastases had been assessed previously using whole blood." (PMID 34512731, 2021). "The interval between diagnosis and pregnancy, the TSH levels during pregnancy or thyroglobulin level before conception had no statistically significant impact on the progression of thyroid carcinoma." (PMID 34122688, 2021). "For patients with thyroid cancer who received thyroidectomy with or without ablative radioactive I-131 therapy, serum thyroglobulin is defined as a cancer biomarker during follow-up." (PMID 32612576, 2020). "Rosiglitazone was also assessed for patients with thyroglobulin-positive and radioiodine-negative differentiated thyroid cancer." (PMID 31614690, 2019). "The autoimmune response within the context of an antitumor immune response would be confirmed by the presence of anti-TG (AAT) and anti-TPO (ATPO) antibodies in about 20% of patients with thyroid carcinoma, with values twice higher in patients with PTC, compared to the general population." (PMID 31142293, 2019). "The unique features of differentiated thyroid cancer (DTC) cells are: ability to take up iodine, presence of the thyroid-stimulating hormone (TSH) receptor, synthesis of thyroglobulin (Tg) and, in some cases, synthesis of thyroid hormones." (PMID 28617334, 2017). "In our cases nonthyroidal pathologies were suspected since the imaging findings were not corroborated by an elevated thyroglobulin level, which is considered a reliable tumor marker for most well-differentiated thyroid cancers." (PMID 28246564, 2017). "One patient was found to have several spots of cryptic uptake in the neck without other evidence of thyroid cancer, such as thyroglobulin elevation." (PMID 26977418, 2016). "However, that rate drops in poorly differentiated thyroid carcinomas to 86% for TTF-1, 57% for thyroglobulin, and 86% for CK7." (PMID 27774331, 2016). "FDG-PET is useful in patients with metastatic poorly differentiated thyroid cancer, in those with high thyroglobulin levels and in patients negative on 131 I-WBS." (PMID 26452365, 2015). "This approach excludes primary thyroid carcinoma and enables use of 131-I and serum thyroglobulin for surveillance of possible recurrent disease." (PMID 30039072, 2015). "In our case, as I described in case presentation, thyroglobulin and calcitonin indicating thyroid cancer were negative." (PMID 25506006, 2014). "The thyroid carcinoma cells may have strengthened to produce CA19-9, so we reviewed the possibility that the undifferentiated carcinoma produced thyroglobulin and the PTC transformed into undifferentiated thyroid carcinoma." (PMID 24407283, 2014).